AFP (alpha fetoprotein)
Diseases named in the same sentence as AFP in open-access papers (continued):
Sharing a sentence is not in itself a finding about the gene and the disease.
tumor (continued). "We compared the expression of CEA, AFP and PSA in tumor tissue with their serum levels." (PMID 31897235, 2020). "Liquid biopsy, which detects circulating tumor cells or nucleic acids, is a promising alternative to AFP but is not yet widely available." (PMID 33134551, 2020). "Multivariate analysis was performed by using several factors of age <77 years old, albumin level ≥35 g/L, ICGR15 <20 %, Child-Pugh classification A, AFP <100 μg/L, PIVKA-II level <100 mAU/mL, and maximum tumor size <5 cm, which were p<0.1 in univariate analysis." (PMID 33112547, 2020). "Evaluation of tumor markers showed a carcinoembryonic antigen (CEA) level of 5.17 ng/ml with the absence of alpha-fetoprotein (AFP), CA19–9, and CA242." (PMID 32404137, 2020). "The sensitivity and specificity of AFP, a tumor marker widely used in the clinic, are not notably high, and most patients are already in an advanced stage." (PMID 32701483, 2020). "Moreover, we observed that stronger ERBB3 expression was correlated with AFP (p=0.023), GGT (p=0.012), tumor size (p=0.011), tumor thrombus (p=0.047), and TNM stage (p=0.007)." (PMID 32206115, 2020). "Additionally, CENPA mRNA were upregulated in HCC patients with alpha-fetoprotein (AFP) elevation, advanced TNM stage, larger tumor size, advanced AJCC stage, advanced pathology grade, and vascular invasion (all P < 0.05)." (PMID 32337237, 2020). "Aiming at identifying the molecular mechanisms underlying the elevated levels of the serum tumor markers, we performed a pan-cancer analysis of AFP, CEA and PSA to assess the relationship between concentration of serum tumor markers and the expression of their coding genes." (PMID 31897235, 2020). "From the multivariate Cox regression analysis results, age, AFP, tumor size, satellite nodules, SII, and PNI were integrated and used to construct the nomogram, which showed that satellite nodules had the greatest impact on HCC recurrence, followed by age, tumor size, PNI, AFP, and SII." (PMID 33163397, 2020). "Also of note, for some genes, more than one component is present (HTR4 E and S for STES/tumor status, CHIA E and S for LGG/tumor status, AFP E and S for LGG/tumor status)." (PMID 32625238, 2020). "Abnormal serum tumor marker levels for NSE were seen in 13 (27.1%) of 48, proGRP in 3 (17.6%) of 17, CA125 in 6 (13.3%) of 45, CA19-9 in 5 (11.9%) of 42, CEA in 4 (7.1%) of 56, SCC in 4 (7.1%) of 56, AFP in 0 (0%) of 5, and CYFRA in 0 (0%) of 2 patients." (PMID 33088427, 2020). "The TRAIN score, also based on intention-to-treat data, was not tested here because based on “dynamic” AFP and tumor radiological modifications following LRT (and thus not at first referral)." (PMID 32075133, 2020). "AFP interaction with RAR was observed in tumour tissues with high serum AFP, but not in adjacent non‐cancerous liver tissues or tumour tissues with low serum AFP." (PMID 33090723, 2020). "The present study also demonstrated that FPR moderately increased with tumor size and BCLC stage of AFP-NHCC, demonstrating that this biological indicator may be related to the invasive phenotype of the disease." (PMID 32190001, 2020). "In addition, CENPA mRNA overexpression was correlated with AFP elevation, advanced TNM stage, and larger tumor size (all P < 0.05)." (PMID 32337237, 2020). "Additionally, the levels of serum AFP and PIVKA-II, and the γ-GT/ALT ratio were positively correlated with tumour sizes in patients with HBV-related HCC." (PMID 32782270, 2020). "The baseline tumor burden, such as the size of the largest tumor, the number of tumors, and AFP were not statistically different." (PMID 32442193, 2020). "Two baseline covariates, serum alpha-fetoprotein (AFP) level (IU/ml) and diameter of main tumor (mm), were considered important prognostic factors for HCC, and thus were standardized and used to predict survival at 12 months after baseline using logistic regression." (PMID 32711455, 2020).
tumor (continued). "Similarly, knocking down AFP expression inhibited human HCC cell proliferation and tumor growth by inducing apoptosis." (PMID 33009373, 2020). "A cluster of stem cell-associated microRNAs has been reported to outperform traditional tumor markers in newly diagnosed TGCTs, but the value of these microRNAs to differentiate between specific and unspecific AFP elevations, has never been reported." (PMID 31906360, 2020). "Clinical admission, in daily urology practice, is usually due to painless testicular mass, while serum tumor markers (human chorionic gonadotropin (HCG), alpha-fetoprotein (AFP) and lactate dehydrogenase (LDH) and scrotal ultrasonography are used for definitive diagnosis." (PMID 32022510, 2020). "AFP and OCT3/4 are the characteristic tumor makers for GCTs." (PMID 32064359, 2020). "The aim of the study was to evaluate the diagnostic value of PIVKA-II and AFP in the diagnosis of HBV-related HCC and futher analysis the level of AFP and PIVKA-II in HBV-related HCC patients with different clinicopathologic characteristics such as tumor differentiation and vascular invasion." (PMID 33292429, 2020). "In addition, the radiomics nomogram was developed based on the following five variables: α-fetoprotein (AFP), platelet-to-lymphocyte ratio (PLR), largest tumor size, microvascular invasion (MVI) and radiomics score (Rad-score)." (PMID 33198809, 2020). "AFP level is the most frequently used tumor marker for HCC; however, in the absence of AFP elevation, the diagnosis can be difficult." (PMID 32493393, 2020). "We therefore excluded AFP and TPSA from the tumor markers under consideration as OM markers." (PMID 32685054, 2020). "Tumor cells were positive for AFP and Hep par 1 (HEP) stains but negative for cytokeratin 19 (CK19)." (PMID 32235007, 2020). "It is commonly reported for AFP to have low sensitivity in early stage HCC as AFP is only secreted by certain molecular subtypes of HCC, and in those which do, AFP levels positively correlate with tumor size, number, differentiation and vascular invasion." (PMID 32374744, 2020). "Factors including type of gastric resection, tumor differentiation, elevated serum AFP and serum ferritin had no significance." (PMID 33256690, 2020). "Measurement of other tumor markers lactate dehydrogenase, alpha-fetoprotein, β-human chorionic gonadotropin, and CA 19-9 was not done because of financial limitations." (PMID 32878645, 2020). "At immunohistochemical analysis, both tumor components were negative for germ cell markers (AFP, SALL4, and Glypican-3), while they showed distinctive expression of Müllerian and intestinal markers." (PMID 32781666, 2020). "Although the univariate analysis used in this study showed that multiple tumor nodules and AFP > 20 ng/ml were predictors of undesirable PFS and OS, none of these factors were identified as independent predictors in the multivariate analysis." (PMID 32070301, 2020). "Finally, the optimal predictors for OS encompassed age, tumor size, APRI, NLR, and PLR, while those for PFS were gender, age, TNM stage, PHT, AFP, and APRI." (PMID 33046985, 2020). "The distributions of MVI status, age, sex, tumor location, tumor maximum diameter, tumor number, and AFP level were not significantly different." (PMID 32567245, 2020). "Regarding tumor markers, there was no statistical difference in serum AFP levels between the two groups." (PMID 33330098, 2020). "However, diagnosis of HCC using conventional tumor markers has yielded unsatisfactory results: the sensitivity and specificity for differentiation of HCC were 39–64% and 76–91% for AFP, and 41–77% and 72–98% for PIVKA-II, respectively." (PMID 33171811, 2020). "As determined from evaluation of module-trait relationships, the brown and turquoise modules showed greater significance in relation to clinical information, compared with the other modules, in particular, main tumor size, TNM stage, and AFP level critical for prognosis of HCC patients." (PMID 33133125, 2020).
tumor (continued). "However, AFP is only elevated in about half of the HCC patients and significant tumor burden limits its usefulness in screening and operable therapy." (PMID 32518728, 2020). "When AFP and PIVKA-II were used as the individual tumor marker, the areas under the ROC curve (AUC) of HBV-related HCC diagnosis were 0.765 (95% CI, 0.713 ~ 0.8170) for AFP, 0.901 (95% CI, 0.868 ~ 0.935) for PIVKA-II, and 0.917 (95% CI, 0.886 ~ 0.948) for AFP and PIVKA-II simultaneously." (PMID 33292429, 2020). "In addition to GLR > 56.0, the adverse factors of postoperative OS and PFS included multiple tumor nodules, tumor size > 5 cm, MVI and AFP > 20 ng/ml." (PMID 32070301, 2020). "Our results also showed that the γ-GT/ALT ratio was positively correlated with tumour size, indicating that the γ-GT/ALT ratio may be another indicator for monitoring the progression of HBV-related HCC, similar to PIVKA-II and AFP." (PMID 32782270, 2020). "Although several clinical characteristics have listed into the criteria for predicting the prognosis of HCC patients, such as tumor diameters, TNM stage, and AFP, these classification schemes are limited to become common predictors for HCC patients due to dissatisfactory sensitivity and specificity." (PMID 33062075, 2020). "However, other involved predictors including AFP (AUC = 0.521), ALT (AUC = 0.456), differentiation (AUC = 0.611), tumor number (AUC = 0.602), and tumor size (AUC = 501) showed unsatisfactory performance." (PMID 32426271, 2020). "Concurrently elevated CA19.9 and AFP in a radiologically diagnosed PLC, or elevation in a biomarker discordant with the features on the imaging may indicate that the tumor is cHCC-ICC." (PMID 33102226, 2020). "The tumor markers (CA199, CEA and AFP) were normal in both probands." (PMID 31754975, 2020). "Western blot and qRT‐PCR results showed that AFP was detected in tumour tissues with high AFP serum, but not in adjacent non‐cancerous liver tissues, or HCC tissues with low serum AFP levels." (PMID 33090723, 2020). "The distributions of tumor size, tumor differentiation, multinodularity, and AFP level did not significantly contribute to HCC recurrence." (PMID 31614906, 2019). "They proposed pre-, post-, and combo-MORAL scores to predict tumor recurrence after LT, using the neutrophil-lymphocyte ratio (NLR), AFP, and tumor size, all of which were superior to the MC at predicting recurrence for patients with HCC at a single center in United States." (PMID 31484287, 2019). "Cucchetti A et.al16 found that preoperative serum alpha-fetoprotein (AFP), tumor number, size, and volume were related to tumor grade and MVI in HCC after hepatic resection and liver transplantation and built a preoperative artificial neural network (ANN) to predict it." (PMID 31632502, 2019). "Bloods and tumour markers such as AFP, CEA, CA 19-9 and CA125 are often normal or non-specific and have no diagnostic value even when elevated." (PMID 30731302, 2019). "Chemerin did not correlate with the tumor markers carcinoembryonic antigen, carbohydrate antigen 19-9 and alpha-fetoprotein in both cohorts and was not changed with tumor-node-metastasis stage in HCC." (PMID 31409008, 2019). "Regarding tumour marker elevation rates in nonseminomas, AFP had the highest rate with 60.1% of our cases." (PMID 31275973, 2019). "Alpha-fetoprotein (AFP), a marker of HCC, was significantly higher in Nlrp12-/- tumor tissue." (PMID 30990169, 2019). "Tumor necrosis and viable cell content in the tumor were identified as prognostic markers of disease progression, as were the well-known HCC prognostic markers of disease progression, alpha-fetoprotein and Glypican-3 expression." (PMID 30922327, 2019). "In this study, liver markers (AFP, Hepatocyte, Glypican-3, and GS) and colon markers (CK20, CAD17, CDX2, β-catenin, and SATB2) were used for staining of xenograft-derived tumours, with the result that all markers were either expressed only weakly, or were not express at all." (PMID 31367188, 2019).
tumor (continued). "After 18 months, during which the tumor remained silent and he was followed closely without treatment, his AFP and PIVKA-II levels rapidly elevated to 21,490 ng/ml and 1444 mAU/ml (respectively), and enhanced CT showed tumor progression." (PMID 31878937, 2019). "Single intraperitoneal administration of NDEA significantly (p < 0.05) elevated liver function enzymes ALT, AST, GGT, LDH, ALP, TBA, TBil, and levels of tumor markers CEA, AFP, TSGF, TNF‐α in serum compared to normal control rats, suggesting the presence of metabolic disorders in NDEA group animals." (PMID 31428352, 2019). "In a multivariate survival analysis that included all variables except for surgery type, tumor stage was found to be an independent factor for OS, but AFP status was still not an independent factor of OS." (PMID 31651371, 2019). "The univariate analysis results showed that NDRG2 and LDHA protein levels are closely related to overall survival of HCC patients independent of age, gender, AFP, tumor size and HBsAg." (PMID 31523182, 2019). "A working hypothesis that we have tested here, is that each or any of CRP, PLR or NLR might be related to indices of tumour aggressiveness, namely MTD, AFP, PVT and multifocality, as an explanation of their prognostic ability." (PMID 30662766, 2019). "Patients’ gender and preoperative tumor markers of AFP & CA19–9 were not significantly different between patients with “high MLVD” or “low MLVD”." (PMID 30849953, 2019). "In summary, when there is no indication of residual tumors, patients with elevated AFP should be managed by surveillance instead of additional tumor-related interventions to avoid experiencing unnecessary acute and chronic toxicity." (PMID 31836006, 2019). "Therefore, effective tools are required to predict tumor diameter and prognosis of HCC patients with preoperative serum AFP ≤200 ng/mL." (PMID 31662990, 2019). "AFP and PIVKA-II may also be related to tumor burden, but the pathophysiologic mechanism is still unknown." (PMID 31681607, 2019). "CSF cytology and tumor markers studies, human chorionic gonadotropin, and alpha-fetoprotein were negative." (PMID 30660187, 2019). "For amplicon 2, we observed that the mean methylation level of DNAH17 in tumor tissues was significantly down‐regulated in patients with tumor thrombus (58.5% vs 78.5%, P = 0.0063) and negative AFP (64.5% vs 73.2%, P = 0.0334)." (PMID 30575322, 2019). "The receptor of alpha-fetoprotein, a tumor marker, is expressed on the surface of many tumor cells, but not in normal human tissues." (PMID 31374911, 2019). "Ca levels inversely correlated with the level of the cancer antigen 19-9 (CA 19-9) tumor marker but not with the carcinoembryonic antigen (CEA) or alpha fetoprotein (AFP) tumor markers or the CaSR genotypes." (PMID 31534963, 2019). "Serum AFP was immediately normalized after surgery and no sign of tumor recurrence has been noted 2 years postoperatively." (PMID 31281709, 2019). "The MoRAL score (11 × PIVKA+ 2 × AFP), using serum alpha-fetoprotein (AFP) and protein induced by vitamin K absence-II (PIVKA-II) levels, could predict tumor recurrence after LDLT and identify patients with low recurrence and long-term OS potential." (PMID 31484287, 2019). "After orchiectomy, the AFP levels were persistently elevated but a very low AFP-L3% indicated no residual or recurrent tumour." (PMID 31652641, 2019). "Risk factors associated with short OS included African–American ethnicity, an age of 2–4 years, distant disease at diagnosis, large tumor size (> 5 cm in diameter), positive AFP status, and not receiving surgery." (PMID 31651371, 2019). "Tumor marker tests were also done, and this showed that her cancer antigen-125 (CA 125) was elevated at 225U/ml (normal range <35.1U/ml) but cancer antigen 19-9 (CA 19-9), carcinoembryonic antigen (CEA) and alpha-fetoprotein (AFP) were within normal limits." (PMID 31280066, 2019).
tumor (continued). "Other signalling pathways significantly deregulated in AFP-high tumours and worthy of further analysis include IGF2–IGFR, mTOR, NOTCH and BAP1." (PMID 31285588, 2019). "AFP-specific liver-resident CD8+ T cells also showed weaker cytotoxicity in tumor site than those in non-tumor site." (PMID 31134088, 2019). "No benefits regarding improvement of patient selection were observed in terms of NRI when a response to neoadjuvant treatment was added to the AFP model, the Metroticket 2.0 model, the TTV/AFP criteria, the Warsaw criteria, or simply to tumor size, number, and AFP." (PMID 31520204, 2019). "Notably, as albumin / CRP ratio was significant associated with other parameters, we therefore performed subgroup analysis according to tumor size, TNM stage, treatment exposure, serum AFP level, and platelet / CRP (platelet to CRP ratio)." (PMID 31164099, 2019). "AFP level (15.03 ± 21.60 vs. 19.02 ± 28.85, p = 0.526) and largest tumor size (2.83 ± 1.48 vs. 3.15 ± 1.77, p = 0.596) were not significantly different between nonrecurrence and recurrence groups." (PMID 31730015, 2019). "Similarly, tumor markers, such as enolase (NSE), carcinoembryonic antigen, and CA-199, lack specificity and sensitivity, except for serum AFP, the level of which is suggestive of disease activity." (PMID 31725669, 2019). "All tumour markers, including B-HCG, AFP, CA 19-9, CEA, and CA 19-9, were within the normal range." (PMID 31220682, 2019). "Lower AFP levels indicate either more favorable tumor characteristics (microvascular invasion, differentiation), less tumor burden, or non-cirrhotic background, which all imply an early HCC stage." (PMID 30894157, 2019). "The patients achieving CPR were matched in a 1:1 ratio with the patients who did not achieve CPR using a propensity score based on tumor number, tumor size, and AFP." (PMID 31520204, 2019). "Six patients had positive tumor markers (ß-HCG and/or AFP) in the CSF at diagnosis." (PMID 31860688, 2019). "However, the tumor markers increased (LDH: 2301 U/l, AFP: 1757.7 ng/ml, b-HCG: 1177684 mIU/ml), and a change in consciousness (Glasgow Coma Scale: E1V1M1) was noted." (PMID 30912892, 2019). "HAC is defined by the minimum criteria of characteristic hepatoid area regardless of its proportion within the tumor mass or AFP production in WHO classification." (PMID 31915699, 2019). "The radiomics nomogram was constructed with the radiomics score, AFP level, gross vascular invasion and non-smooth tumour margin." (PMID 31088553, 2019). "Its high expression was related to tumor size, TNM stage, vascular invasion, and relapse and predicted a poor prognosis but was not involved in the AFP level, portal vein tumor thrombosis, tumor differentiation, gender and age." (PMID 31691514, 2019). "Our results indicate that the combined use of a triplex microRNA panel based on the three miRNAs miR-21, miR-122 and miR-192 and AFP levels significantly improve HCC surveillance in HBV carriers, especially in LC patients with normal AFP levels or HCC patients with small tumor sizes." (PMID 29672637, 2018). "AFP has been widely used as the tumor marker for HCC but does not differentiate the complex etiology of HCC." (PMID 30087805, 2018). "However, the AFP levels were significantly higher in the PVT positive patients, for all 3 tumor size groups, as was tumor multifocality." (PMID 30009156, 2018). "AFP and CA19-9 are well-known and widely used serum biomarkers for tumor diagnosis." (PMID 29459779, 2018). "Tumor markers were taken serially; initial AFP was 9.4 ng/mL (normal values, <10.0 ng/mL), and during follow-up, AFP values were as follows: 7.3, 3.17, and 4.8ng/mL." (PMID 30241223, 2018). "Univariate analysis revealed that tumor size ≥5 cm, multiple tumor numbers, AFP ≥ 20 μg/L, AFP ≥ 400 μg/L, tumor thrombus, and no post-surgical intravenous VC administration were significantly associated with shorter DFS." (PMID 29872720, 2018).